BRAF (B-Raf proto-oncogene, serine/threonine kinase)
Diseases named in the same sentence as BRAF in open-access papers (continued):
Sharing a sentence is not in itself a finding about the gene and the disease.
ameloblastoma (continued). "In the fifth edition of the WHO Classification of Head and Neck Tumours, the adenoid ameloblastoma was added as a new recognized entity separate from solid ameloblastoma, because it does not share the BRAF p.V600E mutations found in other ameloblastomas." (PMID 39430655, 2024). "Furthermore, it is crucial to emphasize that the immunohistochemical technique targeting BRAF V600 can provide valuable assistance in the differential diagnosis of ameloblastomas, particularly when distinguishing them from cystic lesions." (PMID 38615253, 2024). "Among the unicystic ameloblastomas (n=30), 27 cases (90.0%) were positive for BRAF V600E." (PMID 38615253, 2024). "However, it is important to note that the use of BRAF inhibitor therapies in ameloblastomas is still in its early stages." (PMID 38021761, 2023). "Since both drugs are currently not approved for the treatment of BRAF-V600E-mutated ameloblastoma, only isolated case reports on off-label use can be found in the literature." (PMID 37115331, 2023). "Therefore, the development of BRAF-V600E-specific inhibitors represents a promising approach to improve the treatment of ameloblastoma in addition to surgery." (PMID 37646022, 2023). "Although long-term studies on BRAF inhibitors in BRAF-V600E-mutated ameloblastoma are lacking, we see their use to reduce tumor size with consecutive surgical treatment as a reasonable option for therapy." (PMID 37115331, 2023). "Similarly, another report showed a notable reduction in tumor volume in a multiply recurrent ameloblastoma of the mandible in response to single BRAF inhibition therapy with dabrafenib." (PMID 36127985, 2022). "The BRAF V600E mutation was revealed only in ameloblastoma samples, regardless of the detection method." (PMID 35468886, 2022). "Notably, B‐RAF proto-oncogene serine/threonine kinase (BRAF) and KRAS proto-oncogene GTPase (KRAS) pathogenic mutations have been reported in a high proportion of ameloblastoma and ameloblastoma-related tumors and adenomatoid odontogenic tumors, respectively." (PMID 36378285, 2022). "Regarding molecular updates, BRAF p.V600E mutations found in ameloblastomas have not been found in dentigerous cysts." (PMID 35578902, 2022). "Unlike ameloblastoma, BRAF mutations only occur in ~1.8% of HNSCC, and the clinical responsiveness of BRAF-mutated HNSCC patients to BRAF inhibition remains under-explored." (PMID 35296678, 2022). "There is no consensus on the association of BRAF p.V600E mutation with ameloblastoma clinicopathological features, including location, age, histology, as well as clinical behavior." (PMID 35048058, 2021). "Although the molecular pathogenesis of ameloblastomas has not been entirely elucidated, the high frequency of BRAF p.V600E mutation strongly supports such mutation as a therapeutic target in a large proportion of these tumors." (PMID 35048058, 2021). "Notably, B-Raf proto-oncogene serine/threonine kinase (BRAF) and KRAS proto-oncogene GTPase (KRAS) pathogenic mutations have been reported in a high proportion of ameloblastomas and adenomatoid odontogenic tumors, respectively." (PMID 35048058, 2021). "We suggest that a severe somatic mutation on the gene network of cell proliferation other than BRAF V600E, namely second hit, may contribute to the tumorigenesis of Ameloblastoma." (PMID 33395399, 2021). "The prevalence of BRAF V600E in ameloblastoma ranges from 46 to 90%, with a mean value of 68%." (PMID 35048068, 2021). "BRAF p.V600E was detected in 83% (5/6) of unicystic ameloblastomas." (PMID 35048058, 2021). "They further reported the presence of BRAF p.V600E mutation in 67% (23/34) of ameloblastomas by using VE1 immunohistochemistry in cases not suitable for molecular evaluation." (PMID 35048058, 2021). "Key words:Conventional ameloblastoma, BRAF V600E, recurrence." (PMID 32388526, 2020).
ameloblastoma (continued). "After 20 weeks, both the primary oral and pulmonary metastases were responding to treatment, suggesting that BRAF-V600E may be a therapeutic target for ameloblastoma, and targeted drug therapy may be used for AC with BRAF-V600E mutations." (PMID 33176823, 2020). "We also confirm highly significant phenotypic differences in these two types of ameloblastomas as BRAF-mutant cases occurred preferentially in the mandible and at a much younger age (mean age 42 years) than SMO-mutant cases occurring preferentially in the maxilla at an older age (mean age 67 years)." (PMID 29388014, 2018). "Cortical expansion was prominent in ameloblastomas with BRAF or multiple gene mutations, but SMO-mutated tumors never revealed cortical expansion (p = 0.028)." (PMID 29388014, 2018). "Notably, CTNNB1 Ser37Cys and CTNNB1 Gly34Glu were found in addition to BRAF Val600Glu in ameloblastoma cases #19 and #20, respectively." (PMID 28658279, 2017). "BRAF-V600E mutant ameloblastoma might be as frequent as up to 40%, and BRAF-targeted therapy has shown to rescue a patient suffering from malignant BRAF-V600E mutant ameloblastoma." (PMID 27965463, 2017). "In addition, as in cell culture anti-EGFR treatment was proved effective for a subset of ameloblastomas (i.e. those BRAF wild-type), our findings bring to light a possible resistance mechanism to anti-EGFR therapy in such tumors, as shown for other neoplasms." (PMID 25991665, 2015). "In this sense, molecular targeted therapy may be useful in aggressive and recurrent cases and in vitro experiments pointed to anti-EGFR therapy as an option for the treatment of a subset of BRAF wild-type ameloblastomas." (PMID 25991665, 2015). "Interestingly, activating mutation in the BRAF p.V600E gene essentially is associated with ameloblastoma, but expression of its mutated protein product has not been described in OKC." (PMID 40893989, 2025). "However, not all ameloblastomas present the BRAF V600E mutation, so patient selection based on genetic profiling will be important to optimize treatment efficacy." (PMID 39274556, 2024). "The mutation of BRAF V600E may be present in ameloblastomas regardless of differences in prognostic and clinicopathological factors." (PMID 38615253, 2024). "For the unicystic ameloblastomas, in the present study, it was observed positive immunoexpression of BRAF V600E for either luminal, intraluminal and mural subtypes, confirming that these three histological subtypes may be positive for BRAF V600E mutation, as previously defined." (PMID 38615253, 2024). "In the case of unicystic ameloblastoma, no additional mutations to BRAF V600E have been reported." (PMID 38021761, 2023). "Interestingly, in contrast to other intraosseous ameloblastomas, BRAF p.V600E mutations have not been found in AA." (PMID 35578902, 2022). "In this study, we first compared two different antibodies for precise detection of SOX2 in ameloblastomas, then explored the immunohistological staining patterns of SOX2 across the variants of ameloblastoma and verified their concordance to the sequencing results of BRAF." (PMID 35055392, 2022). "Together with the previous observation that most Ameloblastoma occurred in adult or mandible carried BRAF V600E somatic mutation, we inferred that disruption of hub gene BRAF is essential, but not sufficient, to the tumorigenesis of adult mandibular Ameloblastoma." (PMID 33395399, 2021). "Additionally, BRAF mutations have been reported by some authors to predominantly occur in non-plexiform histologic type ameloblastoma, while conversely others reported BRAF mutations predominance in plexiform type." (PMID 35048058, 2021).
ameloblastoma (continued). "In addition, the BRAF V600E mutation is reported to occur in 62% of ameloblastomas and ameloblastic fibromas/fibrodentinomas but is not present in other odontogenic tumors." (PMID 31340860, 2019). "At the molecular level, mutations in the mitogen-activated protein kinase (MAPK) pathway, including BRAF V600E, FGFR2, and NRAS, have been identified in ameloblastomas, including PA." (PMID 41030734, 2025). "Preliminary clinical experience with BRAF inhibitors, including our group’s work, either as a monotherapy or in combination with MEK inhibitors, has already yielded encouraging results in ameloblastomas." (PMID 41364259, 2025). "While there is morphological overlap with AOT and conventional ameloblastoma, it has been shown that AdAM does not exhibit the KRAS and BRAF mutations seen in these two entities, respectively." (PMID 41306250, 2025). "Additionally, there seemed to be potential cooperation between the RAF1-MEK/ERK-ARL4C axis and the BRAF V600E-MEK/ERK pathway, contributing to the advancement of ameloblastoma." (PMID 38021761, 2023). "Reduction in the tumor mass has also been reported by using dual therapy with BRAF/MEK inhibitors, i.e., dabrafenib and trametinib, in metastatic ameloblastomas and monotherapy, i.e., dabrafenib or vemurafenib, in recurrent and metastatic ameloblastomas." (PMID 35048058, 2021). "Although new molecular medicine demonstrates personalized targeted therapy for ameloblastoma, it seems that based on lack of large scale clinical trials, evaluation of the wide clinical application of BRAF inhibitors has a long way." (PMID 32388526, 2020). "To further investigate the characterization of ameloblastoma cells, we established the ameloblastoma cell line AMU‐AM1 and the corresponding fibroblast cell line AM7‐F from ameloblastoma patient No.7 with BRAF V600E mutation." (PMID 32096304, 2020). "The anatomical site, histological type of the tumour, sex and age of the patient, as well as BRAF-V600E and SMO-L412F mutations known to be common in ameloblastoma, were found to be independent of the level of ncRNA detected here." (PMID 27965463, 2017). "The lack of BRAF reactivity and the finding of nuclear β catenin reactivity in these tumors calls into question their relation to ameloblastoma and whether adenoid ameloblastoma is the best designation for this new tumor." (PMID 35578902, 2022). "In ameloblastoma without BRAF Val600Glu, we found NRAS Gln61Arg, which is in agreement with a previous report showing that RAS mutations (including NRAS Gln61Arg) and BRAF Val600Glu are mutually exclusive." (PMID 28658279, 2017). "Additionally, clinical factors of the studied ameloblastomas that could influence the expression of BRAF V600E, such as tumor location, were not taken into account, and it could be a factor influencing the studied cases in this sample." (PMID 38615253, 2024). "In addition, all BRAF-wild type ameloblastomas also tested negative by immunohistochemistry." (PMID 38615253, 2024). "Aside from the SMO mutations, APC mutations have been detected in 3/6 ameloblastomas, and CTNNB1, PIK3CA, SMARCB1, PTEN, CDKN2A mutations have been reported in a few cases and tend to occur in a non-mutually exclusive manner with BRAF p.V600E mutation and with each other." (PMID 35048058, 2021). "SOX2-positive cells were found in all cases regardless of BRAF status, with an average of 22.5% SOX2-positive cells in ameloblastomas." (PMID 35055392, 2022).
cholangiocarcinoma (52 papers, 2009 to 2026). A carcinoma that arises from the intrahepatic biliary tree (intrahepatic cholangiocarcinoma) or from the junction, or adjacent to the junction, of the right and left hepatic ducts (hilar cholangiocarcinoma). "Dabrafenib, in combination with Trametinib, is recommended for patients with all subtypes of progressive BRAF V600E mutation-positive cholangiocarcinoma." (PMID 40909948, 2025). "What is the prevalence of BRAF variant subtypes and their association with disease characteristics, prognosis, and targeted therapy response in patients with intrahepatic cholangiocarcinoma?" (PMID 36867406, 2023). "The combination therapy of the BRAF inhibitor, dabrafenib, and the MEK inhibitor, trametinib, has been studied in BRAF V600E-mutated cholangiocarcinoma." (PMID 38203714, 2023). "A phase II single-arm study evaluated BRAF and MEK inhibitors (Dabrafenib and Trametinib, respectively) for cholangiocarcinoma with a BRAF V600E mutation." (PMID 38203635, 2023). "A study using drug screens in patient-derived organoids with different BRAF variants showed encouraging results with BRAF inhibitors in patients with advanced cholangiocarcinoma." (PMID 38203635, 2023). "BRAF mutation has been identified as a risk factor of cholangiocarcinoma and was most common in “Double-Hit” phenotype." (PMID 35401671, 2022). "Results showed that the combination had a 47% objective response in patients with BRAF V600E–mutated cholangiocarcinoma." (PMID 34638259, 2021). "These patients have a higher stage of tumor at resection, greater likelihood of lymph node involvement, and worse overall survival compared with non-BRAF mutated cholangiocarcinoma." (PMID 34439216, 2021). "Ongoing study of these pathways as well as others found to be implicated in cholangiocarcinoma including map kinase pathway, hepatocyte growth factor, BRAF, and platelet derived growth factor hopefully will lead to effective targeted therapy." (PMID 26089873, 2015). "We also briefly review the current knowledge of the genomics of cholangiocarcinoma with a focus on BRAF mutations, and make a point of the importance of the establishment of a molecular tumour board for personalized genomic medicine approaches." (PMID 25435907, 2014). "When assessing differences by tumor type, cholangiocarcinoma had the highest rate of BRAF alterations (> 5%) including the highest rate of BRAFV600E/class I alterations compared to other tumor types (P < .01)." (PMID 40163685, 2025). "Commonly associated genomic mutations associated with cholangiocarcinoma include KRAS, BRAF, p52, and SMAD4 genes." (PMID 38903278, 2024). "Genetic alterations detected in cholangiocarcinomas include fusions and mutations in FGFR2, mutations in IDH1 and KRAS, the BRAF V600E mutation, and ERBB2 amplification." (PMID 37108676, 2023). "Ivosidenib shows efficacity in IDH1 mutant cholangiocarcinoma and BRAF inhibitors dabrafenib and trametinib in patients with BRAF V600E mutations." (PMID 35484217, 2022). "Other ongoing trials (NCT01713972, NCT01902173) are also assessing dual MEK/BRAF inhibition in patients with BRAF‐mutant cholangiocarcinoma and shall help elucidate the role of this strategy in these patients." (PMID 33660222, 2021). "BRAF V600E mutations occurred in 3–7% of iCCA cases and were associated with poorer prognosis, while HER2 amplification or overexpression occurred in 5–20% of cholangiocarcinoma cases." (PMID 41373672, 2025).
cholangiocarcinoma (continued). "A high prevalence of BRAF V600E mutations was found in 53% of BDA, which may progress to cholangiocarcinoma." (PMID 39553064, 2024). "ERBB2 amplification was the most common predictive marker in gastroesophageal adenocarcinoma, and recent targeted therapy approvals and guideline updates had a significant impact for patients with cholangiocarcinoma and actionable findings in IDH1 (11.2%), FGFR2 (8.1%), or BRAF (1.8%)." (PMID 37682776, 2024). "BRAF, erb-b2 receptor tyrosine kinase 2 (ERBB2), fibroblast growth factor receptor 2 (FGFR2), and isocitrate dehydrogenase 1 (IDH1) genes have been reported as therapeutically relevant genomic alterations in cholangiocarcinoma patients." (PMID 37108676, 2023). "Gene alterations involving IDH (isocitrate dehydrogenase gene), FGFR (fibroblast growth factor receptor), BRAF (v-RAF murine sarcoma viral oncogene homolog B1),HER2 (human epidermal growth factor receptor 2) can decisively influence the proliferation and development of cholangiocarcinoma." (PMID 38846220, 2024). "It is noteworthy that BRAF, which also negatively correlates with SOCS1, has been previously reported to be commonly found in cholangiocarcinoma but not in HCC." (PMID 32807134, 2020).